SFTPA2 (surfactant protein A2)
Diseases named in the same sentence as SFTPA2 in open-access papers (continued):
Sharing a sentence is not in itself a finding about the gene and the disease.
cancer (10 papers, 2015 to 2024). A tumor composed of atypical neoplastic, often pleomorphic cells that invade other tissues. "Most cancer cells in the GG components expressed SFTPA1 and SFTPA2, although cancer cells in the S components of different individuals had diverse distribution patterns." (PMID 35874770, 2022). "The activated SFTPA2 not only can help signaling transduction in EGFR signaling but also can allow cancer cells to clean the pathogens through expressing Surfactant Protein A2 (SFTPA2) to survive in early stage LADC." (PMID 31217907, 2019). "Similar to the overall transcriptional profile of cancer cells in the GG component samples, surfactant-associated proteins (SFTPA1, SFTPA2, SFTPB, SFTPC, and SFTPD) were highly expressed, and the expression level was higher than that of other cancer cell subclusters of the GG component samples." (PMID 35874770, 2022). "GGN cancer cells express significantly higher levels of surfactant-related proteins than SN cancer cells, such as surfactant protein (SFTP) A1, SFTPA2, and SFTPB." (PMID 37745301, 2023). "Furthermore, cancer cells in GGN highly expressed alveolar type II (AT2) cell-related marker genes (SFTPA1, SFTPA2, SFTPB, ABCaC3), suggesting that cancer cells in GGN might originate from AT2 cells." (PMID 37745301, 2023).
tumor (5 papers, 2017 to 2024). "Although SP-A was detectable in tumour cells from heterozygous patients, transfection of A549 cells with any of the mutated SFTPA2 variants revealed poor protein expression, in contrast to the cells transfected with wild-type gene." (PMID 39335088, 2024). "Besides, our results also showed that the protein SFTPA2, which is involved in the clearance of pathogens in response to lipopolysaccharide (LPS), is activated by several epigenetic modifications in the early stage of LADC suggesting that tumor cells may affected by the pathogens." (PMID 31217907, 2019).
adenocarcinoma (3 papers, 2022 to 2024). A common cancer characterized by the presence of malignant glandular cells. "The major clinical implication so far described in SRG mutations relates to the high frequency (37%) of lung carcinoma (mostly of the adenocarcinoma type) alone (12%) or in combination with pulmonary fibrosis (25%) in SFTPA1/SFTPA2 adult carriers." (PMID 36552935, 2022).
bacterial infection (3 papers, 2019 to 2025). "Second, the Basal.MUC16 cluster showed a significant increase (adjusted p < 0.05) in genes associated with bacterial infection (PDZD3, SFTPA2, PIK3C2B), cytokine signaling (TRIM31, SERPINB2), and apoptosis (BCL2L15, VIL1)." (PMID 39935174, 2025).
infectious disease (3 papers, 2011 to 2022). A disorder directly resulting from the presence and activity of a microbial, viral, or parasitic agent in humans. "Nonetheless, associations of SFTPA1 and SFTPA2 SNPs and haplotypes with infectious diseases other than RSV underline the role of SP-A1 and SP-A2 in innate immunity and host defense functions." (PMID 35903101, 2022). "Only a few studies have addressed the role of the genetic variability at SFTPA1, and SFTPA2 in infectious diseases." (PMID 21310059, 2011).
SFTPA2 also shares sentences with these, for which no sentence is quoted: cystic fibrosis (3 papers); otitis media (3); co-infection (2); fungal infection (2); RSV bronchiolitis (2); tuberculosis (2); airway hyperresponsiveness (1); alveolar proteinosis (1); Angelman syndrome (1); bacterial pneumonia (1); breast carcinoma (1); bronchopulmonary dysplasia (1); chronic lung disease (1); coronary heart disease (1); diabetes mellitus (1); diarrheal disease (1); eosinophilia (1); flu (1); hypertriglyceridemia (1); ischemic stroke (1); kidney disease (1); leukaemia (1); non-small cell lung carcinoma (1); pneumonia (1); Prader-Willi syndrome (1); prostate carcinoma (1); respiratory infection (1); squamous cell carcinoma (1); swine influenza (1); vascular Ehlers-Danlos syndrome (1).